IL6 (interleukin 6)
Diseases named in the same sentence as IL6 in open-access papers (continued):
Sharing a sentence is not in itself a finding about the gene and the disease.
cancer (continued). "A comparison of serum concentrations of four pro-inflammatory factors (e.g., IL-6, IL-1β, Chemokine (C-X-C Motif) Ligand 8(CXCL8)/IL-8, and TNF-α) in advanced-stage cancer patients showed that IL-1β levels correlated more strongly with clinical characteristics than those of IL-6." (PMID 33557173, 2021). "Over expression of IL-6 has been noted in almost all kinds of cancer." (PMID 34441972, 2021). "Moreover, IL-6 induces severe immune and metabolic alterations, such as cachexia, which characterize advanced cancer and contribute to CRA pathogenesis, and which can be prevented with anti-IL-6 monoclonal antibodies." (PMID 33535496, 2021). "Additionally, the contact bone marrow MSC-leukemic cell-VLA-4 and VCAM-I mediated increases factors contributing to cancer cell survival like IL-8, IL-6, VCAM-1, and CCL2, known to correlate with high infiltration of macrophages promoting cancer cell growth." (PMID 34680425, 2021). "There are several mechanisms by which IL-6 drives cancer progression." (PMID 33923292, 2021). "In addition, IL-6 levels have been shown to be prognostic indicators of survival and predictors of a response to therapy in several different types of cancer." (PMID 34131122, 2021). "The role of IL-6 in cancer is complex and includes autocrine and paracrine mechanisms." (PMID 34018387, 2021). "Conversely, adding neutralizing antibody either targeting IL-6 or IL-6R could efficiently block the induction of LRG1 mediated by CAFs, supporting that IL-6 was the essential effector derived from CAFs to promote LRG1 expression in cancer cells." (PMID 34930899, 2021). "Besides, CDKN2C and ID2 are downregulated while IL6, BIRC3, PLAT, PPARG, and CEBPB are upregulated in three candidate TCM associated with Transcriptional misregulation in the cancer pathway." (PMID 34490085, 2021). "Taken together, our study provides the impetus to discover new strategies, for instance, the development of efficient agents, including JAK2/STAT3 inhibitors and humanized monoclonal antibodies against IL6 to re-sensitize resistant NPC cells or other cancers that were resistant to chemotherapy." (PMID 34094941, 2021). "Interestingly, PLA2G7 protein and activity levels were more efficient to discriminate between cachectic and non‐cachectic cancer patients than IL‐6 and GDF‐15, two other factors proposed as biomarkers for CCx diagnosis." (PMID 34427055, 2021). "In other words, TIM-4 is an essential molecule in IL-6 overexpressed cancers and enhancing metastasis, therefore, pursuing it could turn out to be an effective pharmacological goal in IL-6 excessively pronounced cancers." (PMID 34336101, 2021). "Interleukin 6 (IL-6) is one of the main inflammatory mediators in cancer pathogenesis." (PMID 34578920, 2021). "In our study, we highlight ERK5 as a promising target for cancer therapies since ERK5 modulates not only the cancer cell viability but also the IL-6 production, which is involved in the regulation of type-1 immunity probably through the downregulation of IL-12p70 secretion from DCs." (PMID 34671021, 2021). "Cancer-associated fibroblasts (CAFs) secrete growth factors, e.g., hepatocyte growth factor (HGF), epidermal growth factor (EGF) and cytokines, e.g., interleukin 6 (IL-6), which activate oncogenic signaling pathways in cancer cells, resulting in chemoresistance." (PMID 33918653, 2021). "While the pro-immunogenic conditions present after doxorubicin treatment are favorable for the clearance of leukemic cells, microenvironmental IL-6 production—which is increased by the presence of leukemic cells—suppresses the expected anti-cancer immune responses." (PMID 34711820, 2021). "Recently, we have highlighted how blocking chronic inflammation, primarily driven by IL-6, may improve the efficacy of the currently available immunotherapy in cancer patients." (PMID 33550983, 2021). "Cancer cells-derived IL-6 enhancing the activity and expansion of MDSCs." (PMID 34095111, 2021).
cancer (continued). "Cancer cells also produce interleukin-6 (IL-6) to activate signal transducer and activator of transcription 3 (STAT3) to induce hypoxia-inducible factor-1alpha (HIF-1α), VEGF, and C-C motif ligand (CCL) 5 expression in lymphatic ECs (LECs) within premetastatic niches to promote metastasis." (PMID 36046433, 2021). "Activation of the IL-6/STAT3 pathway can block antitumour immunity in cancers." (PMID 33855091, 2021). "IL-6 is a well-known inflammatory cytokine that promotes cancer growth and metastasis." (PMID 34589133, 2021). "Furthermore, CUR can also cause NF-κB downregulation and suppress the interleukin-6 (IL-6)-induced STAT3 phosphorylation, which can eventually result in the suppression of cancer cell proliferation." (PMID 33800000, 2021). "BCL2, VEGFA and IL-6 were found to be enriched in pathways in cancer." (PMID 33510225, 2021). "Activation of IL-6 signalling pathways in cancer cells stimulates cell proliferation and migration." (PMID 33758206, 2021). "LIF has been shown to transmit biological information through a heterodimer receptor complex comprising LIF receptor and Interleukin 6 signal transducer in a variety of inflammatory processes, including acute phase reaction, hematopoiesis, bone metabolism, and cancer progression." (PMID 34781940, 2021). "Interestingly, the induction by TGFβ of IL11, a cytokine of the IL6/GP130 family involved in multiple cancer hallmarks, including cell migration and invasion, is greatly enhanced by decitabine." (PMID 34571856, 2021). "A recent systematic review and meta-analysis has described a relationship between chronic inflammation, as measured by inflammatory circulating biomarkers (including C-reactive protein (CRP) and interleukin-6 (IL-6)) and an increased cancer incidence, including CRC." (PMID 35008324, 2021). "Studies have shown that inhibition of the process of autophagy in cancer stem cells may lead to a decrease in the secretion of IL-6." (PMID 33804163, 2021). "Interleukin-6 (IL-6) – together with IL-1β and TNFα – is one of the major inflammatory cytokines, which is elevated in most if not all inflammatory states and has also been recognized as a frequent growth factor in many cancers." (PMID 34141712, 2021). "In contrast, the inflammatory CAFs (iCAFs), named for their chemokine secreting capability, were found distant from cancer cells, expressed significantly lower levels of αSMA, and instead were characterized by secretion of factors such as Il-6, Il-11, LIF, CXCL1 and CXCL2." (PMID 34638468, 2021). "Furthermore, EGFR-TKI treatment increased IL-6 secretion in cancer cells, suggesting aggravation of lung injury." (PMID 33466795, 2021). "Thus, targeting hyperactivated IL‐6/IL‐27‐JAK‐STAT3 pathway is beneficial in the treatment of certain cancers." (PMID 33277798, 2021). "IL‐6, CXCL1 and TGFβ2 are known pro‐tumorigenic factors associated with cancer progression." (PMID 34216174, 2021). "The IL6/JAK/STAT3 pathway plays an important role in the signal transduction processes, which are associated with cell proliferation and the invasive phenotype of cancers." (PMID 35008199, 2021). "Moreover, to definitively evaluate the prognostic and predictive value of CRP and IL-6, their concentrations should be analyzed with relation to the overall and cancer-specific survival rate." (PMID 34441316, 2021). "Studies have shown that CAFs can enhance EMT and cisplatin resistance in non-small cell lung cancer induced by transforming growth factor β by releasing high levels of IL-6, while cisplatin, in turn, promotes cancer cells to produce transforming growth factor β, resulting in CAF activation." (PMID 34447750, 2021). "Interleukin-6 (IL-6) is a crucial component of the cancer microenvironment." (PMID 34681685, 2021). "In previous studies, IL6 was generally considered as an important cancer-promoting molecule." (PMID 34568032, 2021). "IL6 is deregulated in many cancers, with increased serum levels indicating a poor prognosis." (PMID 34411141, 2021).
cancer (continued). "Moreover, in cancer cachexia, inflammatory cytokines, such as IL-6 derived from cancer cells, act on hepatocytes to increase CRP production and increase protein catabolism." (PMID 33757453, 2021). "However, it should be noted that IL-6 can be secreted from other compartments, such as cancer cells and immune cells, and can affect PDAC growth and progression, and therefore, systemic depletion of IL-6 will affect CAF-independent pathways in PDAC as well." (PMID 34948209, 2021). "Moreover, CAF-derived IL-6 secretion induces resistance to trastuzumab (a monoclonal antibody against HER2) by cancer stem cell expansion and apoptosis reduction via NF-κB, JAK/STAT3, and PI3K/AKT signaling pathways." (PMID 34337083, 2021). "IL-6 overexpression has been observed in many types of cancer." (PMID 33670492, 2021). "Finally, in the cancer microenvironment, hypoxia and interleukins (mainly IL-6 and IL-8) also lead to cancer cell EMT." (PMID 34067395, 2021). "Thus, neutralizing either IL-6 or related signaling pathways represent an attractive therapeutic target in cancer." (PMID 34445170, 2021). "Moreover, L-carnitine reduced the serum levels of IL-1 and IL-6, factors known to induce cancer cachexia." (PMID 34724970, 2021). "IL-6 is often upregulated in cancers and is a key cytokine for tumorigenesis and metastasis." (PMID 33824280, 2021). "Importantly, JAK2 directly phosphorylates BECN1 at Y333, leading to an enhanced BECN1-VPS34 interaction and autophagy, a mechanism by which IL-6 regulates cancer chemotherapy resistance." (PMID 34131122, 2021). "Interleukin 6 (IL-6) is connected to more aggressive and invasive types of cancer." (PMID 34641563, 2021). "Naringenin, a major citrus peel flavonoid was also found to suppress the upregulation of matrix metalloproteinase-9 as well as tumor necrosis factor-α which mediated the release of IL-6 and IL-8 posing a potential impact on cancer cell migration and metastasis." (PMID 33782546, 2021). "These therapies have important effects on innate and adaptive immune pathways, which may suppose relevant changes into cancer immunosurveillance mechanisms, especially TNFi, which predominantly target IL-1 and IL-6 in cancer pathways." (PMID 34685480, 2021). "However, in a mouse model, the combined blockade of IL-6 and PD-1/PD-L1 signaling was shown to foster vigorous T-cell responses and decreased the cancer’s immunosuppressive activity." (PMID 33531609, 2021). "One of the most studied cytokines in cancer research is IL-6." (PMID 34572947, 2021). "The critical protumor role of IL-6 in cancer, including OSCC, is well-known." (PMID 35048056, 2021). "Our study thus demonstrates that a hint of caution is warranted in selecting mouse models for cancer cachexia, as overrepresentation of certain circulating factors such as IL6 may occur when exclusively using the C26 mouse model." (PMID 35008253, 2021). "IL-6 is a central mediator of cancer cell-stromal cell interactions in PDAC." (PMID 33858491, 2021). "Moreover, IL-6 secreted by activated fibroblasts in cancer stroma induces EMT of gastric cancer cells via JAK2/STAT3." (PMID 34207510, 2021). "Notably, the interleukin-6 (IL6) cytokine family has been reported to be involved in cancer invasion and proliferation." (PMID 34094941, 2021). "We further investigated whether patients with intratumoral CD45+Rab37+IL-6+ expression profile correlated with cancer progression and poor prognosis." (PMID 34093869, 2021). "Similarly, IL-6 and OSM are linked to decreased overall and disease-free survival in various cancer types, in part due to their role in EMP and metastasis." (PMID 34361105, 2021). "However, there appears to be dearth of studies exhaustively investigating the epigenetic modulations of IL-6 and its receptor complex in cancer." (PMID 34576335, 2021). "IL-6 is also an important molecular link between inflammation and cancer." (PMID 33578830, 2021).
cancer (continued). "Additionally, IL-6 is also well described as a regulator of inflammatory and immune responses in cancer." (PMID 34948097, 2021). "Moreover, it has been suggested that the elevated serum levels of IL-6 are correlated with disease severity and a worse clinical outcome in cancer patients." (PMID 33461943, 2021). "IL-6 is a pro-inflammatory cytokine that functions as a growth factor for cancer cells." (PMID 33718235, 2021). "Now we know that IL-6 plays a prominent role in many inflammatory states and cancer." (PMID 34141712, 2021). "Interestingly, the high IL-6 levels in the TME serve to associate chronic inflammation and cancer progression." (PMID 34178680, 2021). "CXCR4 and IL-6 are key-regulators of inflammation and leucocyte migration in immunity and cancer and could potentially play a role in systemic immunity." (PMID 34417915, 2021). "Epigenetic processes also control the IL-6-mediated induction of cancer cell stemness." (PMID 34722553, 2021). "IL-6 overexpression has been detected in a large number of cancer types." (PMID 34445479, 2021). "In addition, GBM cancer stem cells have been found to respond to perturbations caused by hypoxia, the inhibition of STAT3 phosphorylation, and IL-6 stimulation." (PMID 34576141, 2021). "Moreover, estrogen promotes the secretion of IL-6 derived from CAFs, which acts as the immunosuppression cytokine and inhibit the cancer immunity." (PMID 34098945, 2021). "Besides E3 ligases, previous studies have demonstrated the role of IL-6 in the progression of cancer-mediated muscle wasting." (PMID 33925786, 2021). "Cancer- or hypoxia-activated Schwann cells release nociceptive mediators such as IL-6, TNFα, CXCL2, and IL-811,15; these mediators could sensitize primary afferent neurons to cause pain." (PMID 33469141, 2021). "Given that up to 85% (819/934) of the cancer cell lines in the Cancer Cell Line Encyclopedia expressed STING, we speculate that STING-dependent IL-6 induction in response to DNA damage is very frequent in cancer cells." (PMID 35087822, 2021). "IL-6 plays a key regulatory role in the pathogenesis of many types of cancer." (PMID 34056002, 2021). "Omental adipose tissue in cancer patients presents an increased IL-6 production." (PMID 34440886, 2021). "Thus, IL-6 derived by PGCCs is capable of reprogramming both cancer and stromal cells and contributes to the evolution and remodeling of cancer." (PMID 34588424, 2021). "Furthermore, IL-6 is among the cytokines released in large amounts following T-cell therapies for cancer (i.e., adoptive cell transfer ACT or CAR-T cell therapy)." (PMID 34335558, 2021). "IL-6 is one of the key mediators of interaction between cancer cells, fibroblasts, and the TME35." (PMID 33758206, 2021). "EVs derived from GC cells could induce polarization via the STAT3 pathway into M2-macrophages, which secrete IL-6 to promote malignancy of cancer cells." (PMID 33509150, 2021). "Treatments targeting IL-6 are approved for clinical use in patients with rheumatoid arthritis and Castleman’s disease, although their use in patients with advanced cancer has yet to be fully realized despite promising results from preclinical models of solid tumors." (PMID 34335558, 2021). "However, we failed to observe these changes in lung specimens, which was probably due to the dilution of IL-6 mRNA expressed by cancer cells from metastases with IL-6 mRNA expression from various normal cells." (PMID 34834397, 2021). "Moreover, IL-6 protects cancer cells from therapy-induced DNA damage, oxidative stress, and apoptosis by facilitating the repair and induction of counter signaling (antioxidant and anti-apoptotic/pro-survival) pathways." (PMID 34178680, 2021). "However, the ethanolic CN extracts prevented the smoldering inflammation between cancer cells and immune cells by reducing the level of pro-inflammatory cytokines, such as IL-6, IL-1β and TNF-α." (PMID 34379689, 2021).
cancer (continued). "The evidence on the role of IL6 in cancer has been reviewed extensively." (PMID 34834425, 2021). "In addition, there have been some interesting reports demonstrating a significant association between inflammation and cancer, resulting from high IL-6 levels in the cancer or disease affected environments." (PMID 34900966, 2021). "In tumor microenvironment, the chaotic interplay between cancer and host cells may lead to an increase of factors and cytokines such as TNFα, IL-6, PTHrp which eventually results in an impaired muscle homeostasis." (PMID 33804536, 2021). "Once stress is removed from the host, IL-6 synthesis finishes, but uncontrolled excessive or persistent IL-6 production plays a pathological role in the development of acute severe inflammatory diseases or chronic diseases and cancers." (PMID 33628091, 2021). "Particularly, the activation of the IL-6/JAK/STAT3 core axis is observed in many types of cancer." (PMID 34440220, 2021). "IL-6 is able to induce the expression of EMT-TFs in a wide variety of cancer types." (PMID 34361105, 2021). "After these factors have been activated, they could lead to the recruitment of macrophages mediated by the expression of cytokines and chemokines (TNF-α and IL-6) of cancer cells." (PMID 34965886, 2021). "The innate immune cells of the TME secrete various cytokines such as TNF-α and interleukin-6 (IL-6), which can promote cancer cell survival and induce the expression of vascular endothelial cell adhesion molecules (CAM) that facilitate extravasation of leukocytes." (PMID 33986746, 2021). "As IL1A and IL6 are two important pro-inflammatory cytokines in human cancers, we speculated that the hypoxic stress in the lung tumor promotes the secretion of IL1A and IL6." (PMID 34362882, 2021). "In the context of ICD, IL-6 may impair anti-cancer immunity through the creation of a microenvironment in which an acute inflammatory stimulus from cell death is less likely to generate a productive immune response." (PMID 34711820, 2021). "Furthermore, IL-6 plays a crucial role in cancer progression by activating STAT3 and stimulating the proliferation and migration cancer cells." (PMID 33917793, 2021). "IL-6 level significantly increased in CM from mixed culture of all three cell types (Bar 6), and to a lesser extend in CM derived from co-culture of A549 cancer cells and THP-1 macrophages (Bar 5)." (PMID 34093869, 2021). "Following on the observation that pharmacological inhibition of STING reduced IL-6 production upon topoisomerase 1 inhibition in mouse TC-1 cancer cells, we decided to broadly interrogate the role of STING signaling in the IL-6 response to acute DNA damage in human cancer cells." (PMID 35087822, 2021). "Similarly, positive correlations of PDL1 with cytokines such as TNFα and IL-6 have been reported in other chronic inflammatory diseases including systemic lupus erythematous and cancer." (PMID 34597347, 2021). "This information suggests targeting IL-6/STAT3/cyclin D axis in cancers with low PDS5B might provide a novel therapeutic approach." (PMID 34070827, 2021). "In the pathogenesis of cancer, elevated IL‐6 and IL‐27 could stimulate the activation of JAK1 and JAK2 enzymes, which subsequently mediate tyrosine phosphorylation of STAT3 at Tyr705." (PMID 33277798, 2021). "Furthermore, it is understood that IL-6 and its signaling pathways are substantial players in orchestrating the cancer microenvironment." (PMID 34681685, 2021). "Moreover, stromal IL6 promotes cancer immune-evasive microenvironment through metabolic reprogramming." (PMID 33843442, 2021). "Additionally, IL-15 and IL-6 have known roles in activating NK-cell and T-cells during exercise and ability to facilitate the immune system and promote anti-cancer effects in preclinical models." (PMID 33555464, 2021).